TNF (tumor necrosis factor)
Diseases named in the same sentence as TNF in open-access papers (continued):
Sharing a sentence is not in itself a finding about the gene and the disease.
psoriasis (continued). "For mild plaque psoriasis, treatments usually include topical medications, with biologics (specifically tumor necrosis factor [TNF] inhibitors) used as first‐line treatment for more severe cases of psoriasis." (PMID 34390028, 2021). "The median values of TNF alpha, IL-17 and IL-23 in patients with psoriasis before phototherapy was significantly higher compared to the control group." (PMID 34208603, 2021). "From a histopathological point of view, it is hard to distinguish true psoriasis from a TNFα-induced psoriasiform dermatitis." (PMID 33802483, 2021). "In both disorders there is a higher TNF-α production from macrophages, and more recently the Psoriasis Area and Severity Index (PASI) score was positively correlated with BMI values." (PMID 34947847, 2021). "Infliximab, which is a TNF-α monoclonal antibody applied in psoriasis treatments, appears to inhibit SP-D in murine models of intestinal ischemia/reperfusion or lung injury and relieve tissue injury by decreasing SP-D levels." (PMID 33790889, 2021). "Other investigators found that TNF blockade with adalimumab inhibited M1 polarization and resumed the M1/M2 ratio both ex vivo and in vitro in patients with psoriasis." (PMID 34093562, 2021). "Apart from the context of skin aging, TNF-α is also considered a vital regulator in inflammatory skin diseases such as psoriasis." (PMID 34679744, 2021). "The result showed that five gene sets were significantly enriched in psoriasis samples, including inflammatory response, TNF-α signaling via NF-κB, IFN-α/β response and IL-6/JAK/STAT3 signaling." (PMID 33613635, 2021). "Blocking miR-21 using anti-miR-21 oligos or blocking TNF-α using the anti-TNF-α antibody etanercept can lead to the thickness decrease of psoriasis epidermal cells to varying degrees." (PMID 33975513, 2021). "In psoriasis, in addition to proinflammatory synergism with IL-17 and TNF-α, it interacts with IFN-α, which enhances the expression of its receptor (IL-22R) on keratinocytes." (PMID 34769005, 2021). "TNF-α is key cytokine in psoriasis immune response activation, and also has important impacts on keratinocyte proliferation and the control of endothelium proteins required for T-cell migration." (PMID 34834393, 2021). "Currently, biological therapeutics targeted at TNF-α, IL-12/IL-23, IL-17, and IL-23/IL-39 are approved for the treatment of moderate to severe psoriasis." (PMID 34884596, 2021). "MiR-766-3p was upregulated in both HaCaT cells treated with the psoriasis-related cytokine pool (IL-17A, IL-22, IL-1 alpha, oncostatin M, and TNF-alpha) and tissues." (PMID 34992498, 2021). "Bacterial superinfection, which is rarely seen in psoriasis, is remarkably frequent in anti-TNF-α-induced psoriasiform eczema." (PMID 33802483, 2021). "Certain cytokines such as TNF-α, IL-17, IL-23, and IL-6 play a significant role in the pathogenesis of both psoriasis and uveitis." (PMID 33802255, 2021). "a) Etanercept: Tumour necrosis factor alpha (TNF-alpha) is a pro-inflammatory cytokine involved in the pathogenesis of inflammatory disorders like psoriasis." (PMID 33585138, 2021). "The iatrogenic link between IBD and psoriasis relies on several reports showing the development of psoriatic lesions in IBD patients treated with anti-TNF treatment, such as infliximab (IFX) or adalimumab (ADA)." (PMID 33477990, 2021). "Here we report the discovery and replication of an actionable, predictive biomarker of response to the anti-TNF adalimumab in psoriasis." (PMID 34362923, 2021). "TNF-alpha has gained much attention in psoriasis pathogenesis due to its elevated levels in the blood and skin lesions of the patients." (PMID 33936220, 2021). "On the other hand, the supplementation of Bifidobacterium species, which belong to the Actinobacteria, caused a decrease in the serum concentration of TNFα and C-reactive protein (CRP) in psoriasis patients." (PMID 33924414, 2021).
psoriasis (continued). "Several biologic agents have been approved for treating psoriasis, such as anti-TNF-α agents and IL-12/IL-23 antagonists." (PMID 34083738, 2021). "Patients with psoriasis who have administration of anti-TNF drugs often show an improvement in MetS." (PMID 34367173, 2021). "The pathogenesis of psoriasis is extremely complex and involves numerous immune and inflammatory mediators, including IL-1α, TNF-α, IL-17A, and IL-22." (PMID 34314383, 2021). "In some views, anti-TNF-α antibody is supposed as the first-line treatment for psoriasis with metabolic syndrome." (PMID 34367173, 2021). "In the past decade, several biologics that are primarily aimed at inhibiting TNF-α, blocking IL-12, and IL-23, or interfering with Th17 cell development have been approved for the treatment of psoriasis." (PMID 34354596, 2021). "Psoriasis is a hyperproliferative skin disease with a predominant Th1/Th17 response, with an upregulated concentration of multitude cytokines (TNF-α, IL-1β, IL-12, IL-17A, IL-22, IL-23, interferon-γ, and IL-13)." (PMID 34685480, 2021). "According to the recommendations of the Polish Dermatological Society dated 2018, cyclosporin A (CsA) and biological drugs, among others TNF-α inhibitors (adalimumab), are recommended for the treatment of moderate and severe cases of psoriasis." (PMID 32774143, 2020). "The mRNA expression levels of TNF-α, IL-23p19, and IL-17A, key cytokines involved in the development of psoriasis, were also increased in the IDO2 KO mice." (PMID 32752186, 2020). "T cells and DC infiltrate the epidermis migrating into all layers of the epidermis and as a consequence levels of the pro-inflammatory cytokines IFN-α, IFN-γ, TNF-α, IL-1β, IL-23, and IL-17 are high in psoriasis lesions." (PMID 32708987, 2020). "Pathological T cells and dendritic cells can trigger abnormal keratinocyte proliferation in psoriasis progression via many cytokines, especially TNF-α." (PMID 33321931, 2020). "The cytokine network in psoriasis has been proven by the therapeutic effectiveness of biologic antibodies that block individual cytokines, including TNF-α, IL-23/IL-12p40, anti-IL-23p19, IL-17A, and IL-17 receptor." (PMID 33633737, 2020). "Actually, blocking antibodies against TNF-α, IL-23p19 and IL-17 show remarkable efficacy in psoriasis and/or psoriatic arthritis." (PMID 32456211, 2020). "High abundance of these S100-proteins during psoriasis can be explained especially by the effects of IL-17A, IL-17F, TNF, and IL-1α on S100A8/S100A9 expression, which are all central players in the pathogenesis of psoriasis." (PMID 33643287, 2020). "As the clinical response to anti-IL-23/IL-17A biologics seems better than that to anti-TNF-α biologics in psoriasis, the IL-23/IL-17A axis likely plays a more crucial role than the TNF-α axis in the development of psoriasis." (PMID 32070069, 2020). "The TNF-α pathway also plays a central role in psoriasis, amplifying inflammation in several distinct ways." (PMID 32224981, 2020). "Several studies have identified that overexpression of various cytokines occurred in psoriasis, such as interleukins (ILs), tumor necrosis factor (TNF), and interferon-γ (IFN-γ)." (PMID 32848730, 2020). "TNF-α simultaneously increased the adhesion of keratinocytes and monocytes, which plays a key role in psoriasis." (PMID 32659890, 2020). "Current biologics targeting IL-17, IL-23, and TNF-α play critical roles in the pathogenesis of psoriasis." (PMID 33613558, 2020). "Patients with psoriasis increased their lean (fat-free) mass and fat mass during treatment with anti-TNF-α and patients with RA treated with tocilizumab (an IL-6 inhibitor) for 1 year gained weight significantly, without change in fat mass." (PMID 32962676, 2020). "The key role of TNF-α and IL-1β as cytokines involved in the pathogenesis of psoriasis is well known." (PMID 32708987, 2020).
psoriasis (continued). "Currently, TNF inhibitors are used for psoriasis therapy; however, due to substantially high cost and risk associated with TNF-α inhibitors, these are not commonly used." (PMID 31991752, 2020). "Consistent with this, numerous patients treated with TNF-α blockade have developed seemingly paradoxical autoimmune or inflammatory diseases, with psoriasis induced by anti–TNF-α being a well-documented side effect of this treatment." (PMID 32841223, 2020). "Analysis of the T‐cell infiltrate in paradoxical skin reactions demonstrated a significant reduction of IFN‐γ‐ or TNF‐α‐producing CD3+ cells in paradoxical psoriasis, when compared to chronic psoriasis." (PMID 31577850, 2020). "Patients affected by psoriasis showed high levels of pro-inflammatory cytokines such as TNF-α, IL-6, and IL12 that exacerbate the inflammatory response." (PMID 32708987, 2020). "The immunological pathways involving IL-23 and IL-17A (IL-23/TH17 axis), as well as TNF-α, have been demonstrated to play pivotal roles in the pathogenesis of psoriasis." (PMID 32382290, 2020). "The mixture of IL-17A, IL-22, oncostatin M, IL-1α, and TNF-α (M5) cytokines were used to simulate HaCaT keratinocytes to establish psoriatic keratinocyte model recapitulating some features of psoriasis in vitro." (PMID 33081840, 2020). "The platelet-lowering effect of anti-TNF-α therapy has been reported in patients with other autoimmune diseases such as psoriasis and IBD, and some of them even evolve into drug-induced side effects such as thrombocytopenia." (PMID 33343345, 2020). "TNF-α, an important proinflammatory cytokine, was found to exert great function in psoriasis pathogenesis." (PMID 32493482, 2020). "Anti-TNF agents are highly effective in the treatment of psoriasis, but 2–5% of treated patients develop psoriasis-like skin lesions called “paradoxical psoriasis”." (PMID 32947991, 2020). "These cytokines mediate the potentiation of keratinocytes on psoriatic inflammation, and the use of antibodies against IL-23, TNF-α, and IL-17 in the treatment of psoriasis has shown a key role of these cytokines in the pathogenesis of psoriasis." (PMID 32671018, 2020). "The high therapeutic efficacy of IL-17-, TNF-α-, and IL-23-targeting biologics for treating psoriasis supports the central role of IL-17-producing T-cells in the development of psoriatic inflammation." (PMID 32355189, 2020). "Treatment with biological drugs, especially TNF-α inhibitors, increases the risk of reactivating latent tuberculosis infection (LTBI) in psoriasis patients." (PMID 33270676, 2020). "LL-37 stimulate mDCs to secrete TNF-α and IL-6, and mDCs are able to activate naïve-T cells and induce their polarization to Th1/Th17 cells in psoriasis." (PMID 32509872, 2020). "Inflammatory cytokines, including IL-17, IFN-γ, and TNF-α, are also involved in the inflammatory process of psoriasis." (PMID 32280718, 2020). "Consistently, recent studies conducted on human tissues showed that psoriasis and atherosclerosis exhibit significant overlap of their transcriptomes and in particular those dependent on TNF-α and IFN-γ, thus providing the linking between the two diseases." (PMID 32161545, 2020). "Psoriasis is one of the common chronic inflammatory skin diseases in which inflammatory cytokines such as IL-17 and TNF-α play critical roles." (PMID 32392785, 2020). "Bifidobacterium infantis 35624 administration in psoriasis patients reduced plasma levels of TNF-α and CRP." (PMID 32751360, 2020). "TNF-α concentration in plasma of psoriasis patients with normal secretion (↑83.25%, p ≤ 0.0001) and in plasma of psoriasis patients with hyposalivation (↑100.49%, p ≤ 0.0001) was significantly higher than in the control group." (PMID 32164227, 2020). "The combination therapy attenuates IMQ-induced psoriasis-like inflammation by downregulating the levels of IL-17A, IL-22, IL-23, and TNF-α in the serum and skin and upregulating Treg cells compared with Acar alone or low-dose CsA alone." (PMID 32316255, 2020).
psoriasis (continued). "The application of TNF-α antagonists significantly decreased the levels of inflammatory cytokines in the IMQ-induced psoriasis-like dermatitis model." (PMID 32280718, 2020). "In vivo studies suggested the topical application of TRA and BT dual-loaded liposomal gel had the best ability to reduce the thickness of epidermal and the level of cytokines (TNF-α and IL-6), largely alleviating the symptoms of psoriasis." (PMID 32448273, 2020). "It was previously demonstrated that TNF-α antagonists have high efficacy for the treatment of psoriasis by inhibiting the inflammation cascade triggered by TNF-α." (PMID 32280718, 2020). "To date, five FDA-approved TNF-α inhibitors are being used in routine clinical practice to treat patients with rheumatoid and psoriatic arthritis, psoriasis, ankylosing spondylitis, or Crohn’s disease." (PMID 33053859, 2020). "Although TNF-α blockade is used for management of HS and psoriasis, these 2 inflammatory skin conditions are quite different." (PMID 32841223, 2020). "HaCaT cells were stimulated with a cocktail of five proinflammatory cytokines (M5), including IL-1α, IL-17A, IL-22, oncostatin M, and TNF-α that has been demonstrated as an in vitro model of psoriasis." (PMID 33149756, 2020). "In this study, HPKs were treated with IFN-γ, IL-17A, IL-22 and TNF-α, to generate a psoriasis-like phenotype." (PMID 32316273, 2020). "A substantial number of psoriasis patients had a prescription history of a TNF blocker with methotrexate." (PMID 32203525, 2020). "In conclusion, IL-22 is a key regulator of proliferation and anti-apoptosis in psoriasis through mediating the Bcl-2 family in keratinocytes and interacting with TNF-α and IFN-γ." (PMID 32632545, 2020). "Psoriasis is a chronic inflammatory skin disease characterized by an accelerated tumor necrosis factor-α (TNF-α)/interleukin-23 (IL-23)/IL-17 axis, and hyperproliferation and aberrant differentiation of epidermal keratinocytes." (PMID 32751360, 2020). "IL-8 is able to attract more neutrophils to the lesion site and TNF-α can be found in many inflammatory diseases including psoriasis." (PMID 32993791, 2020). "TNFα plays a role in psoriasis development by synergizing with IL-23 to induce IL-17 producing cells, including ILC3s." (PMID 32153574, 2020). "TNF antagonists, IL-17, and IL-12/23 inhibition with monoclonal antibodies were the main treatment measures of psoriasis." (PMID 32090080, 2020). "S100A7 is induced by calcium, vitamin D, retinoic acid, bacterial products, TNF-α, IL-17A and IL-22, and is involved in the pathogenesis of psoriasis via its chemotactic activity for neutrophils and CD4+ T lymphocytes." (PMID 32947991, 2020). "The HA-modified ethosomes showed specific adhesion CD44 in imiquimod-induced psoriasis-like inflamed skin, and that the increased topical drug delivery of curcumin reduced TNF-α, IL-17A, IL-17F, IL-22, and IL-1β mRNA levels; and lower CCR6 protein expression." (PMID 32848737, 2020). "Tumor necrosis factor (TNF)-α, which is involved in the development of psoriasis, is overproduced by keratinocytes, and excess TNF-α increases Th17 cell generation." (PMID 32316255, 2020). "To test this, we analysed normal human epidermal keratinocytes (NHEKs), a major skin component, stimulated with the key mediators of psoriasis development, TNF-α and IL-17A." (PMID 32194991, 2020). "It was demonstrated that enhanced miR-21 expression in psoriasis lesions initiates a cascade ultimately leading to increased tumor necrosis factor alpha (TNFα) release." (PMID 33291448, 2020). "The activation of NF-κB is mediated by TNF-α, which plays an unquestionable role in the pathogenesis of psoriasis." (PMID 32456228, 2020). "Biological therapies such as tumor necrosis factor (TNF), interleukin (IL) 12/23, and IL-17 inhibitors have revolutionized the management of moderate-to-severe psoriasis, allowing a high proportion of patients to attain clear skin." (PMID 32659978, 2020).
psoriasis (continued). "These cytokines, like TNFα, a cytokine critical for the initiation of psoriasis, and chemokines have functional roles in the inflammatory process of psoriasis." (PMID 33643287, 2020). "TNF-α antagonists like Infliximab hinder osteoclastogenesis via decreasing, theoretically or actually, RANKL, TNF-α, and M-CSF production, while skin irritation like psoriasis and eczema are observed." (PMID 32317967, 2020). "It is known that the frequency of Treg cells increases in the skin of psoriasis patients after topical treatment with steroids, and that anti-TNF-a drugs induce the upregulation of circulating Tregs that correlates with reduction in the disease severity score." (PMID 32630692, 2020). "Psoriasis-related cytokines such as IL-17A and TNF-α induced ET-1 expression in human keratinocytes." (PMID 32528072, 2020). "The mechanism of its action in psoriasis pathogenesis is to prime keratinocytes and neutrophils for enhanced production of proinflammatory cytokines (TNF-α, IL-6, and IL-8)." (PMID 32377165, 2020). "Psoriasis is an immune-mediated disease characterized by dysregulation of several cytokines, such as tumor necrosis factor-alpha (TNF-α)." (PMID 32580408, 2020). "Cytokine receptors have been exploited to construct such logic gates, like in the case of an “AND” gate that uses TNF (tumor necrosis factor) and IL-22 (interleukin 22) receptors to sense psoriasis and to drive anti-inflammatory IL-4 and IL-10 in response." (PMID 33287392, 2020). "Here, we used imiquimod (IMQ) or tumor necrosis factor (TNF)-α to induce a psoriasis-like model in mice or keratinocytes." (PMID 32515468, 2020). "The effects of TNF-α antagonists were examined in a mouse imiquimod- (IMQ-) induced psoriasis-like dermatitis model." (PMID 32280718, 2020). "The expression of ADAMTSL5 and LL37 with DCs, neutrophils, macrophages, and T cells in psoriasis significantly decreases after treatment of IL17 or TNFα blocker." (PMID 33050592, 2020). "In this study, we first showed 1) that the expression of ET-1 was enhanced in IMQ-induced psoriasiform dermatitis as well as human psoriasis and 2) that the psoriasis-related cytokines IL-17 and TNF-α promoted ET-1 production from epidermal keratinocytes." (PMID 32528072, 2020). "Inflammatory markers, that are typical in psoriasis, like TNF-α, IL1β, and mast cell degranulation, as well as occludin and ZO-1 tight junctions (TJs), were examined." (PMID 32708987, 2020). "We noted a positive correlation between TNF-α and NO concentrations in unstimulated saliva of patients with hyposalivation, as well as between IL-2 and NO contents in unstimulated saliva of psoriasis patients with normal saliva secretion." (PMID 32164227, 2020). "Until now, induction of immune cells and keratinocyte apoptosis had been postulated as one possible function of anti-TNF therapies in psoriasis." (PMID 32632545, 2020). "T cell-associated gene (LCK and TRCB1) and inflammatory gene (IL17, IL22 and IFN-γ) activity remains increased in the skin after psoriasis lesions, at least three months after the onset of the treatment with TNF-α inhibitors." (PMID 31963581, 2020). "The human and bacterial RNA complexed with LL-37 not only stimulate PMNs from psoriasis patients that respond via TLR8 by producing TNF-α, IL-6, IL-8, and IL-1β, and NET-release; they also can be released by PMNs." (PMID 32509872, 2020). "In the treatment of moderate to severe psoriasis, cyclosporine A (CsA) conventional therapy is used and biological, anti-cytokine treatment using, for example, anti-TNF drug—adalimumab." (PMID 32774143, 2020). "The response to TNF blockers has been reported to be significantly associated with the TNFAIP3 TG haplotype (order of SNPs: rs2230926, rs610604) in psoriasis." (PMID 33287909, 2020). "Anti-TNF-α antibodies are first-generation biologics that have a strong therapeutic effect on psoriasis and psoriatic arthritis; however, patients sometimes discontinue therapy due to infectious disease." (PMID 32486022, 2020).